IL10 (interleukin 10)
Diseases named in the same sentence as IL10 in open-access papers (continued):
Sharing a sentence is not in itself a finding about the gene and the disease.
melanoma (continued). "A study found that melanoma cells incorporated in the dermal compartment of an hPSkC induce higher IL-10 release." (PMID 38136325, 2023). "The IL‐10 promoter contained TCF binding motifs for regulation by the β‐catenin/TCF‐4 complex in human melanoma." (PMID 35864742, 2023). "In the B-16 melanoma model, IL-10 and IL-35 synergistically promote T cell depletion in the tumor microenvironment (TME) through numerous mechanisms." (PMID 36541788, 2023). "Knockout of the A2A receptor in myeloid cells dampens IL-10 production in TAMs and augments anti-tumor immunity in melanoma model, highlighting the critical role of adenosine signaling in orchestrating myelosuppressive effects in the TME." (PMID 37740232, 2023). "IL-10 can inhibit the antitumor activity of tumor cells and promotes T-cell exhaustion in breast cancer and B16 melanoma models." (PMID 36891319, 2023). "In contrast, the two extracts decreased IL-10 levels in the B16-F10 murine melanoma model, but only P2Et treatment increased TNFα and IFNγ levels, indicating increased activation of the effector immune response." (PMID 38069022, 2023). "Experiments on mouse models of melanoma, B-cell lymphoma, and sarcoma reveal that B-cell and B-cell-derived cytokine IL-10 can suppress anti-tumor immune responses." (PMID 36830675, 2023). "IL-10 administration suppressed tumor growth and resulted in tumor rejection in several tumors, including melanoma, sarcoma, and colorectal cancer." (PMID 36009467, 2022). "It has been demonstrated that tumour Treg lymphocytes are correlated with melanoma growth and progression, their recruitment being performed by cancer cells through IL-10, IL-35, and tumour growth factor β (TGF-β) production in order to escape immunity." (PMID 35334544, 2022). "Activation of HLA-G expression by IL-10 is indicated in melanoma cells, thereby contributing to the tumor escape from immunosurveillance." (PMID 36437782, 2022). "A higher IFN‐γ/IL‐10 ratio is reported in melanoma patients who were responsive to PD‐1 inhibitor therapy." (PMID 35301813, 2022). "iCM induced higher levels of IFN-γ and IL-10 in treated melanoma cells compared to rCM, as well as higher IDO and PD-L1 expression." (PMID 35419291, 2022). "HMGB1, released by melanoma cells, promotes the accumulation of M2-macrophages, which enrich the tumoral microenvironment with IL-10, turning down the tumoral killing." (PMID 36012593, 2022). "The concentrations of IL-1β, TNFα, and IL-10 were assessed in the peripheral blood plasma obtained from the healthy animals (control) and animals bearing S91 melanoma tumors at different stages of growth." (PMID 35053477, 2022). "The production of the immunosuppressive cytokine IL-10 was significantly upregulated in the presence of WM1617 metastatic melanoma cell line-CM and slightly increased after all tumor supernatants and dexamethasone treatment." (PMID 36194602, 2022). "Melanoma susceptibility to immunotherapies is reduced by CAFs production of IL6 and induction of IL10 in melanoma cells, the latter inhibiting antigen-presenting cells and weakening the immune response." (PMID 35558554, 2022). "IL-10 also inhibits the production of many cytokines and suppresses tumor growth and metastasis of human melanoma cells by inhibiting macrophage-derived angiogenic factors." (PMID 36405903, 2022). "By stimulating melanoma cells with IL-10 (20 ng/mL), it was found that the expression of AMPK was significantly decreased in A375 and H1205-lu cells, while the expression of BCL-2 was also significantly increased in H1205-lu cells." (PMID 35893303, 2022). "S91 melanoma growth induced a higher number of IL-10-secreting cells in AIRmax mice (4.857 ± 2.015) than in AIRmin mice (1.949 ± 1.565) and considerably more IL-12-producing spleen cells (AIRmax: 3.500 ± 3.082 versus AIRmin: 0.278 ± 0.507) at 30 days." (PMID 35265317, 2022).
melanoma (continued). "miR-128 has been found to block the p38 MAPK pathway, which inhibits the production and production of IL-6 and IL-10 while increasing the amount of IL-12 in DCs., hence boosting the anti-cancer immunity of DCs and decreasing cancer progression in melanoma." (PMID 36793341, 2022). "Multiple studies have found a positive correlation between IL-10 levels and poor prognosis in various cancers, including melanoma, lung cancer, and T/NK-cell lymphomas." (PMID 35646056, 2022). "Since HMGB1 directly induces IL-10 production in TAMs, blocking IL-10 with a neutralizing antibody led to delayed tumor growth in a B16 mouse melanoma model." (PMID 36012593, 2022). "The IL-10 has been published to be expressed by various melanoma cells, especially metastatic malignancy." (PMID 36194602, 2022). "Further research on the relationship between the melanoma prognosis and IL-10 according to the QOL is needed." (PMID 36405903, 2022). "Following our observations of systemic dysregulation among cytokine-expressing B cells in patients with melanoma, we sought to investigate cytokine expression profiles (regulatory IL-10 and TGF-β, and pro-inflammatory TNF-α) within the TIL-B compartment." (PMID 35909944, 2022). "In the group of melanoma-CM-educated moDCs, TNFα secretion negatively correlated with the ability of moDCs to induce IL-10 producing CD4+CD25+ T cells." (PMID 36194602, 2022). "It was previously thought that melanoma inhibits the killing effect of the immune system by secreting immunosuppressive cytokines including IL-10." (PMID 36212143, 2022). "Using seven-color multiplex immunohistochemistry and automated tissue imaging and analysis of whole tissue sections, we identified varying dynamics for LTA+ and IL-10+ B cell subpopulations during melanoma disease progression." (PMID 34359321, 2021). "4-F-GlcNAc inhibitory efficacy on melanoma growth is driven by higher levels of anti-melanoma CTLs and lower levels of IL-10." (PMID 34680031, 2021). "For example, serum concentration of IL-10 in patients with malignant melanoma can reach as high as 23 ng/ml." (PMID 33708210, 2021). "First, we compared the IL-10-increasing ability of MAFs collected from primary melanoma samples of various Breslow depths." (PMID 34944793, 2021). "Given the poorly recognized but still substantial body of data on pro-inflammatory functions of IL-10 and other IL-10 cytokine family members, our data support further evaluation of B cell-derived IL-10 in human melanoma." (PMID 34359321, 2021). "Compared to parental NK-92 cells, co-incubation of CD276-CAR NK-92 cells with melanoma cells significantly increased secretion of various interleukins, among others, IL-6 (98- to 317-fold) and IL-10 (6- to 15-fold)." (PMID 33925968, 2021). "Increased levels of IL-8 and IL-10 in melanoma, circulating effector memory CD4+ and intratumoral CD8+ T cells in both tumor types were detected after therapy." (PMID 34777395, 2021). "IL10 is expressed not only in immune cells but also in tumors; the functions of IL10 produced from tumor cells were mainly reported in melanoma." (PMID 34344966, 2021). "Prior exposure to primary or cell line-derived melanoma cells greatly promoted the MAFs IL-10 increasing ability." (PMID 34944793, 2021). "IgG4 subclass antibodies are expressed in alternative Th2 environments featuring high IL-10 expression, including several solid tumors such as melanoma." (PMID 33628623, 2021). "In a melanoma model, tumour cells shedding EVs mediated chemotherapy resistance by promoting M2 macrophage polarisation and upregulating IL10 and ARG1 expression in stromal cells." (PMID 33401460, 2021). "We then demonstrated that MAFs indeed are potent inducers of IL-10 production in various macrophage types in vitro, and this process is greatly augmented by the presence of treatment-naïve and chemotherapy-treated melanoma cells." (PMID 34944793, 2021).
melanoma (continued). "After DHA treatment, the levels of IL-6 and IL-10 in serum and melanoma of melanoma bearing mice are significantly decreased, while IFN-γ is significantly increased." (PMID 34692496, 2021). "In another study, crocin (250 and 500 μg/kg) attenuated VEGF, MMP-2, and MMP-9 expressions and TNF-α and IL-6 levels while it elevated IL-10 level in melanoma metastatic model in C57BL/6 mice." (PMID 34956439, 2021). "LTA+ and IL-10+ B cell subpopulations were mainly found in the intratumoral stromal septa and the peritumoral stroma of melanoma metastases." (PMID 34359321, 2021). "In contrast to these studies, our results now only show low numbers of IL-10+ B cells in human melanoma, numbers which were considerably lower than those of LTA+ B cells." (PMID 34359321, 2021). "In patients with locoregionally advanced melanoma treated with neoadjuvant ipilimumab, a high baseline IL-10 level appeared a biomarker for progression, and high TGF-β levels for non-progression." (PMID 34502325, 2021). "IL-10 contributes to cancer growth by suppressing natural anti-cancer immunity and can also interfere with anti-melanoma immunotherapies." (PMID 34944793, 2021). "It is noteworthy that the stimulation of DCs with CM from vemurafenib-resistant cells induced a significant release of IL-10, an immunosuppressive cytokine whose expression correlates with melanoma progression and metastasis." (PMID 33467521, 2021). "Melanoma derived-IL-10 reduces immune response by suppressing the function of antigen-presenting cells (APCs), blocking the production of pro-inflammatory cytokines, and downregulating the expression of co-stimulatory molecules and MHC class II." (PMID 34067929, 2021). "Such exposure to melanoma supernatants augmented the ability of MAFs to increase IL-10 production in THP-1 cells." (PMID 34944793, 2021). "IL-6, highly produced also by MAFs, can promote the expression of the immunomodulatory cytokine IL-10 in melanoma cells." (PMID 34067929, 2021). "It is likely that there are other immunosuppressive elements, e.g., IL-10 or TGFβ or PD-1 mediated inhibitory activity, influencing immune response intensity in melanoma patients." (PMID 35069536, 2021). "Through the production of IL-10, melanoma cells prevent maturation of DCs, suppress production of Th1-inducing cytokine IL-12 in DCs, and inhibit their antigen-presenting properties, attenuating generation of effector CD4+Th1 and CD8+CTLs." (PMID 32695181, 2020). "Melanoma cells can inhibit T cell proliferation through IL-10 and IFN-γ induction, in a Treg-dependent manner." (PMID 33287312, 2020). "Our data also revealed the importance of IL‐10 and IL‐6 in predicting metastatic progression, albeit they provide a subleading and fluctuating contribution to melanoma outcome prediction compared to Breslow thickness and serum levels of IL‐4, GM‐CSF, and DCD." (PMID 32485045, 2020). "A future prospective validation of IFN-γ/IL-10 ratio in a larger population of advanced melanoma patients must be performed in order to better select patients who are candidate for anti-PD-1 therapy." (PMID 33077770, 2020). "Consistent with this, supernatants from metastasis-derived melanoma cells were significantly more effective in down-regulating CD1a on moDCs in an IL-10-dependent fashion in comparison to primary melanoma cultures." (PMID 32507967, 2020). "Further analyses show that SK1 knockdown in melanoma tumors potently reduced the production of various immunosuppressive cytokines such as TGFβ, IL10, CCL17, and CCL22, which is in line with the strong decrease of Treg tumor infiltration." (PMID 31974367, 2020). "Consistent with previous studies reporting elevated levels of the immune suppressive factor IL-10 in the serum of advanced melanoma patients, we also showed its up-regulated secretion from the Mel-RhS." (PMID 32507967, 2020). "Statistically significant differential plasma expression in melanoma patients vs. controls has been reported for IL-2, IL-6, and IL-10." (PMID 33302400, 2020).
melanoma (continued). "It was reported that the Wnt/β-catenin pathway activated by human melanoma cells exerts an immunosuppressive effect on DCs and cytotoxic T cells, mainly through the induction of IL-10 secretion." (PMID 33171792, 2020). "IL-6 plays a central role in melanoma development and enhances the IL-10 production via STAT3-dependent signaling." (PMID 32508531, 2020). "Tumor cells in melanomas, lung carcinomas and certain types of lymphomas are able to produce IL-10 suggesting that the production of immunosuppressive cytokines such as IL-10 is one of the mechanisms for tumor evasion of immune rejection." (PMID 33312693, 2020). "The overexpression of IL-10 in B16(F10) cells accelerates tumor growth through reduced presentation of melanoma antigens." (PMID 33287312, 2020). "Multiple studies have found that IL-10 levels is positively correlated with poor prognosis in patients with lung cancer, melanoma, and T/NK-cell lymphoma." (PMID 33614473, 2020). "In another murine melanoma model, selective deletion of A2A receptors in myeloid cells leads to significantly reduced IL-10 production by MDSCs, an increase in activated CD8+ T cells and NK cells, and delayed primary tumor growth and metastasis." (PMID 32793192, 2020). "iNKT cells can also be rendered unable to suppress melanoma metastasis, or will even enhance metastasis, after pretreatment with α-GalCer, through the induction of IL-10 producing iNKT10 cells." (PMID 30881361, 2019). "The correlation of high IL-10 expression with melanoma progression provides further evidence that this chemokine is another important influencer in the vertical growth phase of melanoma." (PMID 31861163, 2019). "In this context, IL-6 is central in melanoma development and also enhances the IL-10 production via STAT-3-dependent signaling." (PMID 31750245, 2019). "IL-10 is expressed in immune cells present in melanomas (melanophages, lymphocytes) and also by tumor cells as invasion proceeds, fostering an immunosuppressive environment favorable for tumor development." (PMID 29963229, 2018). "Previous studies showed that migration and invasion of HT-29 cell line was not significantly changed following treatment with IL-10, however, in murine models of breast and melanoma cancers IL-10 showed anti-metastatic effects." (PMID 29256156, 2018). "In support of the cancer-promoting role, elevated expression of IL-10 was observed in many cancers, including non-melanoma and melanoma skin cancer." (PMID 29467923, 2018). "For example, ICOSL expressed on mesenchymal stem cells, and melanoma cells, can promote the induction and expansion of IL-10-producing CD4+ T cells." (PMID 30319662, 2018). "A number of studies have showed that IL-10 reduces the synthesis level of VEGF, TNF-α, or MMP-9, which leads to a prevention of angiogenesis associated with the growth of the tumour; such as melanoma and prostate cancer." (PMID 30458011, 2018). "Further, IL-6 induces melanoma differentiation whereas IL-10 supports the enrichment of undifferentiated melanoma stem like compartment." (PMID 28137308, 2017). "IgG4+ B cells and IgG4s were detected in melanoma tumor microenvironments together with IL-10, IL-4 and vascular endothelial growth factor (VEGF)." (PMID 28507802, 2017). "In humans, we found circulatory IL-10 strongly elevated in late stages of melanoma positively correlating with the circulatory elevated T lymphocyte CD4+ and CD25+ with FOXP3 expression." (PMID 29318162, 2017). "We also showed that the functional and phenotypic alterations that are observed in melanoma cells post contact with B-1 lymphocytes were dependent on the IL-10 production by the latter." (PMID 29145406, 2017). "Recent studies have shown that in melanoma-bearing mice, myeloid-derived suppressor cells favor tumor growth associated to elevated MCP-1 and IL-10." (PMID 29318162, 2017).
melanoma (continued). "IL-10 has been shown to inhibit the production of IL-1, IL-6, IL-8, TNF-α and forced expression of IL-10 suppressed VEGF and MMP-9, secreted by tumor-associated macrophages in melanoma model." (PMID 29219852, 2017). "In this context, the maturation and priming of DCs is influenced by stimuli of the microenvironment where they suffer of an immature/tolerogenic phenotype induced by VEGF, IL-8 and IL-10 produced by melanoma cells." (PMID 29285320, 2017). "IL-27 expression correlated with that of PD-L1 and IL-10 in melanoma samples, and IL-27 induced IL-10 and PD-L1 expression in melanoma cells in vitro." (PMID 28255204, 2017). "For instance, TGF-beta and IL-10, found in melanoma cell nests, have been described to reduce the development of DCs." (PMID 28331853, 2017). "Multiple studies have found a positive correlation between IL-10 levels and poor prognosis in melanoma, likely due to immunosuppressive properties of IL-10." (PMID 29137411, 2017). "In summary, our findings demonstrate that endogenous IL-10 influences the expression of claudin-10 in B-1 lymphocytes and implicate the axis IL-10/claudin-10 to augment the aggressive behavior of the B16F10 melanoma cells upon contact with B-1 lymphocytes." (PMID 29145406, 2017). "First, our data indicate that IL-10 is required for the efficient Th1 and Th17 immune inhibition that impairs Treg recruitment to peripheral organs and B16/F10 melanoma tumors." (PMID 27075020, 2016). "We took advantage of C57BL/6 IL-10 “gene knockout” mice to conduct a thorough investigation of the roles of IL-10 and Tregs in B16/F10 melanoma." (PMID 27075020, 2016). "Surprisingly, we observed dramatically decreased (P < 0.001) growth of the melanoma tumor in the IL10−/− mice compared with the WT mice." (PMID 27075020, 2016). "Wild-type (WT) or IL-10 knockout (IL-10−/−) mice were implanted with B16/F10 melanoma cells s.c. into the left flank, and tumor volumes were recorded over 15 days." (PMID 27075020, 2016). "In conclusion, we demonstrate that HMGB1, derived from hypoxic tumour cells, significantly contributes to melanoma progression by favouring the accumulation of IL-10-secreting TAMs within the tumour." (PMID 27426915, 2016). "We also observed that HMGB1 directly induced the production of IL-10 in TAMs and that blockade of IL-10 with a neutralizing antibody led to delayed tumour growth in the B16 mouse melanoma model." (PMID 27426915, 2016). "We investigated Treg immunomodulating cytokines that influenced B16/F10 melanoma tumors in immunocompetent and IL-10 knockout mice." (PMID 27075020, 2016). "As the melanoma environment is characterized by high levels of IL-10, we analyzed the effects of miR-15a, miR-185, and miR-211 on the growth of melanoma cells exposed to this cytokine." (PMID 26631117, 2015). "IL-10 has been extensively studied for its ability to affect immune responses against a wide variety of cancers, and, to a lesser extent, also against the melanoma." (PMID 26631117, 2015). "The ability of IL-10 to affect melanoma growth under a variety of conditions renders this cytokine an interesting topic of research in this field, although the mechanisms involved are complex and incompletely understood." (PMID 26631117, 2015). "Data presented here acquire perhaps further relevance in light of a recent paper showing that the expression of IL-10 and IL-10R, despite the great variability, is lower in melanomas compared to normal skin." (PMID 26631117, 2015). "The expression profile of IL-10/IL-10R, miR-15a, miR-185, and miR-211 observed in cutaneous and uveal melanoma tissues exhibited the same trend observed in melanoma cell lines." (PMID 26631117, 2015). "Stimulation of melanoma cells and monocytes by lipopolysaccharide resulted in cytoplasmic translocation of hnRNPD from nucleus and reduced levels of IL-6, IL-10 and TNF-α following activation of MKP-1 (MAPK phosphatase-1)." (PMID 26318153, 2015).